INS (insulin)
Diseases named in the same sentence as INS in open-access papers (continued):
Sharing a sentence is not in itself a finding about the gene and the disease.
Obesity (continued). "Indeed, insulin regulates renal gluconeogenesis by influencing enzyme production or activity associated with the availability of gluconeogenic precursors, an influence anticipated to be diminished or impaired in individuals with MetS or obesity-related insulin resistance." (PMID 40223924, 2025). "Obesity, particularly abdominal obesity, elevates circulating free fatty acids and pro-inflammatory mediators that impair insulin signaling in both peripheral tissues and the central nervous system." (PMID 41282294, 2025). "By modulating FOXO1, anthocyanins not only improve insulin sensitivity but also mitigate the adverse effects of obesity on glucose and lipid metabolism." (PMID 40218884, 2025). "Recently, excessive insulin production (also called hyperinsulinemia) has been attracting attention because of its relation to obesity-induced metabolic disease." (PMID 41009733, 2025). "Litchi chinensis regulated insulin resistance and glucose metabolism and improve zebrafish obesity by modulating Cetobacterium." (PMID 40003065, 2025). "Breast cancer-promoting action of obesity is often attributed to elevated levels of insulin, glucose, inflammatory mediators, and misbalanced estrogen production in adipose tissue under obese conditions." (PMID 40868123, 2025). "Inhibition of IP6K1 helps maintain insulin sensitivity and prevents obesity whilst preserving bone integrity." (PMID 40108027, 2025). "For succinate modulation, promoting bacteria that convert succinate into propionate—such as A. muciniphila and Bifidobacterium spp.—enhances anti-obesity effects by reducing lipogenesis, improving insulin sensitivity, and promoting satiety." (PMID 40183584, 2025). "VDR knockout mice display reduced fat mass, increased energy expenditure, and resistance to HFD-induced obesity, alongside improved glucose tolerance and insulin sensitivity." (PMID 41438090, 2025). "Decreased mitochondrial respiration in VAT associated with reduced insulin sensitivity has been observed in patients with MASLD and obesity." (PMID 40211057, 2025). "This intervention reduces obesity‐related ER stress and enhances both glucose tolerance and insulin sensitivity." (PMID 41157845, 2025). "Obesity likely increases pro-inflammatory cytokines, insulin resistance, and oxidative stress, all of which contribute to periodontal tissue destruction." (PMID 40916006, 2025). "Under healthy conditions, the muscle regulates insulin‐induced whole‐body glucose disposal while in obesity, compromised muscle physiology can occur leading to insulin resistance and reduced energy levels." (PMID 39446089, 2025). "Higher taurine concentrations can lead in beneficial effects since taurine improves glycemic control and insulin sensitivity and it has shown potential anti-obesity properties." (PMID 40690028, 2025). "In individuals with obesity, exercise-responsive EVs appear to carry miRNA cargo involved in improving insulin sensitivity and lipid metabolism, supporting a mechanistic role of EVs in the systemic benefits of physical activity." (PMID 41150813, 2025). "We have previously shown in female mice that muscle-specific ERα knockout (MERKO) reduces oxidative metabolism and insulin sensitivity, and this mouse model recapitulated the obesity-insulin resistance phenotype of whole-body Esr1−/− animals." (PMID 40328250, 2025). "In conclusion, our findings demonstrate the therapeutic potential of tryptamine, a bacterial tryptophan metabolite, in ameliorating obesity and insulin resistance by regulating lipogenesis and lipolysis in adipose tissue." (PMID 39941095, 2025). "To achieve this, we utilized fully differentiated and hypertrophic SGBS cells as a cellular model of obesity, inducing insulin resistance and inflammation by exposing them to exogenous TNF‐α." (PMID 40951581, 2025). ", who reported that the abundance of Prevotella was positively correlated with obesity, blood glucose, and insulin levels." (PMID 40462210, 2025).
Obesity (continued). "Transgenic mice overexpressing Trb3 in adipose tissue demonstrated greater insulin sensitivity and fatty acid oxidation, protecting them from diet-induced obesity." (PMID 40141412, 2025). "These sugar-sweetened beverages contain high levels of artificial sweeteners and fructose, which can lead to rapid increases in blood glucose and insulin levels, followed by hypoglycemia and fat accumulation, thereby contributing to obesity." (PMID 40573138, 2025). "Hyperinsulinaemia, in turn, can lead to weight gain, further perpetuating the cycle of hyperinsulinaemia, obesity, escalating insulin requirements and worsening IR." (PMID 40130476, 2025). "Our findings demonstrate that a B cell-specific conditional Pnoc knockout improves glycemic control and enhances insulin sensitivity in the context of diet-induced obesity, despite comparable adiposity." (PMID 40662198, 2025). "Glucagon-like peptide-1 receptor agonists are pivotal in managing T2DM and obesity, enhancing glycaemic control by boosting insulin secretion, reducing glucagon levels, delaying gastric emptying, and promoting satiety." (PMID 40708853, 2025). "Adiponectin typically inhibits NF-κB signaling and cytokine expression, while improving insulin sensitivity; its decrease in obesity further amplifies inflammatory and metabolic imbalances." (PMID 41301434, 2025). "Maternal high-fat diet also exacerbated obesity in female offspring, accompanied by increased serum leptin levels, decreased insulin sensitivity, destruction of adipose tissue structure, and metabolic and reproductive hormone disorders." (PMID 41220714, 2025). "Other ways of regulating intestinal flora, such as synbiotics, can play an anti-obesity and improve insulin resistance by regulating human intestinal flora." (PMID 41158623, 2025). "Comparing these results with existing literature, the association between obesity and MASLD is well-established, with visceral adiposity driving insulin resistance, hepatic lipid accumulation, and inflammation." (PMID 41183221, 2025). "Research has shown that obesity promotes kidney stone formation not only by altering hormone levels, such as insulin and adipokines, but also by affecting urinary composition, such as increased levels of urinary calcium, oxalate, and uric acid." (PMID 40130163, 2025). "In obese female mice, estrogen treatment improved insulin sensitivity, silenced inflammation and reduced obesity." (PMID 41514592, 2025). "Mechanistically, MSTN inhibition interacts with insulin sensitivity and obesity through both skeletal muscle-dependent and independent mediation." (PMID 39340593, 2025). "CAMK1D has been suggested to play a role for liver gluconeogenesis, fat mass deposition, obesity and reduced insulin sensitivity." (PMID 39754479, 2025). "Anthocyanins have been proven to increase insulin sensitivity, maintain a healthy weight balance, and inhibit the onset of obesity-related metabolic disorders by inhibiting inflammation." (PMID 40218884, 2025). "Managing electrolyte imbalances is essential in obesity management, as imbalances exacerbate hypertension, metabolic acidosis, neuromuscular complications, and insulin resistance." (PMID 40136609, 2025). "In women living with obesity, our meta-analyses suggests that increased insulin and decreased adiponectin concentrations in the maternal circulation are associated with increased GDM risk." (PMID 41019841, 2025). "Obesity impairs insulin signaling via chronic inflammation, lipotoxicity, and metabolic dysregulation, while the synergy of obesity and IR promotes age-related comorbidities (e.g., DM, CVD) that exacerbate systemic frailty." (PMID 41021555, 2025). "Obesity-driven carcinogenesis involves dysregulated lipid metabolism, insulin resistance, inflammation, and adipokine signaling, mechanisms that collectively promote tumor proliferation, migration, angiogenesis, and reduced apoptosis." (PMID 40475001, 2025).
Obesity (continued). "The pericyte specific transmembrane receptor CD248 has been shown to be elevated in adipocytes of insulin‐resistant individuals with obesity." (PMID 40229590, 2025). "BPRPT0245 significantly prevented diet-induced obesity, lowered fasting plasma glucose, improved glucose tolerance, and insulin sensitivity in mice." (PMID 40119175, 2025). "The net result, demonstrated in numerous animal studies and supported by early human trials, is an attenuation of obesity-related phenotypes: less weight gain, lower adiposity, improved insulin sensitivity, and a more anti-inflammatory status." (PMID 41374064, 2025). "In humans, circulating levels of SM species with distinct saturated acyl chains (C18:0, C20:0, C22:0, and C24:0) were found to be closely correlated with the parameters of obesity, insulin resistance, liver function, and lipid metabolism in young obese adults." (PMID 40245983, 2025). "Obesity is known to impair the skeletal muscle’s ability to regulate glucose uptake in response to insulin, which is a critical factor in the development of IR." (PMID 40362714, 2025). "In conclusion, the presence of obesity blunted the adaptive ketogenic response to 48 h of fasting, likely explained at least in part by higher insulin relative to the L-BMI group." (PMID 40662191, 2025). "Experimental inhibition of ceramide synthesis improves insulin sensitivity and alleviates lipotoxic stress in models of obesity and high saturated fat intake." (PMID 40710534, 2025). "The correlation of visceral fat miR-34a with systemic insulin sensitivity in a human population also emphasizes the physiological significance of miR-34a as a novel therapeutic target in obesity and related metabolic diseases." (PMID 41228448, 2025). "The interplay between KATP channel activity and insulin signaling pathways highlights their potential role in the pathophysiology of obesity." (PMID 41394126, 2025). "The mean Matsuda Index was 2.57 ± 1.10 in the obesity group and 10.73 ± 7.27 in the healthy, lean group, representing a >75% lower value in the obesity group (p = .0081), consistent with reduced insulin sensitivity." (PMID 41250958, 2025). "Specifically, THCV reduced adiposity, improved hepatic fat metabolism, and enhanced insulin signaling in both adipocytes and hepatocytes in diet-induced obesity models, while CBD reduced adipogenesis and improved insulin signaling in cultured adipocytes." (PMID 40872492, 2025). "A post-hoc exploratory analysis of the SURPASS-3 study used MRI to assess thigh muscle composition in 246 insulin-naive patients with T2D and obesity, comparing tirzepatide to insulin degludec over 52 weeks." (PMID 41011082, 2025). "Understanding these pathways is crucial for developing therapeutic strategies to mitigate obesity effects and improve insulin sensitivity." (PMID 39762333, 2025). "Inhibition of caspase-1 using genetic or chemical approaches reduces body weight gain and improves insulin sensitivity in high-fat diet (HFD)-induced obesity mouse model." (PMID 40433411, 2025). "Understanding the cellular and molecular mediators of adipose inflammation offers critical insight into the pathogenesis of obesity-related metabolic disease and highlights potential therapeutic targets for restoring insulin sensitivity." (PMID 40699742, 2025). "A higher proportion of participants who were underweight were using insulin, whereas participants with obesity were more likely to be receiving ≥ 3 oral antidiabetic agents." (PMID 41351230, 2025). "Several factors, including obesity, insulin sensitivity, inflammation, genetic factors, and hormones, such as adiponectin and insulin, can affect the production and secretion of omentin-1." (PMID 41153608, 2025). "The pathophysiology of obesity is multifaceted, involving hormonal dysregulation, particularly in hormones like insulin, leptin, and ghrelin, which regulate appetite and metabolism." (PMID 41306340, 2025).
Obesity (continued). "In obesity, elevated FFAs interfere with insulin signaling by impairing the tyrosine phosphorylation of IRS-1, which contributes to the development of IR, hepatic lipid accumulation, and oxidative stress." (PMID 40777174, 2025). "For obesity, drugs such as glucagon-like peptide-1 (GLP-1) receptor agonists promote satiety, reduce appetite, and enhance insulin secretion to stimulate weight loss, improve metabolism, and reduce cardiovascular disease." (PMID 40663389, 2025). "In obesity models, AX reduces adipose tissue inflammation, improves insulin sensitivity, and modulates adipokine secretion, suggesting a multifaceted role in metabolic syndrome prevention." (PMID 41515196, 2025). "In a diet‐induced model of obesity, it was found that despite an increase in basal insulin in both ponies and WB, only ponies developed a degree of steatosis." (PMID 40476757, 2025). "Here, we generated an adipocyte-specific miR-30a transgenic mouse (miR-30afat) model to investigate how obesity-resistant miR-30a expression in WAT sustains insulin sensitivity." (PMID 40471675, 2025). "Other miRNAs, including hsa-miR-519b-3p, hsa-miR-384, hsa-miR-488-3p, and hsa-miR-877-3p, target the key molecules involved in glucose metabolism, insulin resistance, and adipose tissue differentiation, reinforcing their role in obesity pathophysiology." (PMID 40699679, 2025). "Our results highlighted inhibition of PTGR2 as a new effective approach to prevent obesity, improve insulin sensitivity and insulin tolerance, and reduce hepatic steatosis without adverse side effects through increasing endogenous PPARγ ligands." (PMID 40119175, 2025). "This study illustrated the anti-obesity and antidiabetic potential of black bean anthocyanins through an insulin-independent mechanism, simulating inhibition of glucose uptake in the intestine." (PMID 39795230, 2025). "This distinguishes our study from other type 1 diabetes studies, which included individuals with overweight or obesity, high insulin dose requirements or metabolic syndrome features." (PMID 41285865, 2025). "These molecular events foster a chronic inflammatory milieu that disrupts metabolic homeostasis, potentially exacerbating obesity-related complications and insulin signaling dysfunction." (PMID 41424782, 2025). "The biochemical reasoning behind insulin driven obesity includes the profuse signaling in adipocytes which leads to excess fat accumulation." (PMID 40735043, 2025). "Given that zinc plays a crucial role in the synthesis and secretion of insulin, the findings suggest a need for further investigation into the potential involvement of zinc in IR, a common feature of obesity." (PMID 40298814, 2025). "In individuals with T2DM or obesity, impaired insulin function prevents glucose from efficiently entering the cells." (PMID 40072058, 2025). "Exosomes are emerging as crucial mediators of heterotypic cell communication in obesity, influencing immune responses and insulin sensitivity." (PMID 40659888, 2025). "Butyrate activates GPR109A, eliciting anti-inflammatory effects, promoting fat oxidation, and improving insulin sensitivity, highlighting its potential as a target for obesity treatment." (PMID 40295195, 2025). "For improving insulin sensitivity and lowering the threat of obesity, chrononutrition (diet in accordance with natural circadian cycles) plays an important part, and AI's potential was examined by Bajaj and Lata (2024) in this application." (PMID 41019177, 2025). "Alterations in insulin and adipokine signaling, in particular, are crucial pathways through which obesity accelerates EC progression." (PMID 40852190, 2025). "Increasing 15-keto-PGE2 through either genetic disruption or pharmacological inhibition of its degrading enzyme PTGR2 or direct injection of 15-keto-PGE2 into mice improved insulin sensitivity and prevented diet-induced obesity." (PMID 40119175, 2025).
Obesity (continued). "In conclusion, by integrating FF and ERPF into a novel haemodynamic index, we provide evidence that insulin resistance is a key determinant of pressure-driven hyperfiltration dysfunction in severe obesity." (PMID 41282359, 2025). "The current obesity epidemic is also affecting patients with T1D who were typically considered as mostly lean and insulin sensitive." (PMID 40760325, 2025). "Given that obesity is commonly associated with metabolic irregularities, we also employed glucose tolerance test (GTT) and insulin tolerance test (ITT) to assess the role of quercetin in maintaining metabolic homeostasis." (PMID 39888270, 2025). "The ratio of mitochondrial respiration to glycolysis was shifted towards glycolysis in PBMCs from insulin sensitive children with overweight/obesity compared to those with normal weight." (PMID 40525760, 2025). "Adiponectin improves insulin sensitivity, reduces inflammation and fibrosis, and offers cardioprotective, anti-obesity, and hepatoprotective effects." (PMID 40299427, 2025). "Obesity is further often characterized by lower circulating levels of adiponectin, a hepatoprotective insulin-sensitizing adipokine with anti-inflammatory and anti-fibrotic effects, which has been described as a biomarker of MASLD disease severity." (PMID 39826021, 2025). "Individuals with clinical obesity often exhibit elevated insulin and HOMA-IR indices, yet maintain fasting glucose within the normal range or even slightly below that of preclinical individuals, due to compensatory hyperinsulinemia." (PMID 40949120, 2025). "PTP1B deficiency in neurons promotes leanness, prevents diet-induced obesity, and enhances insulin sensitivity." (PMID 40137124, 2025). "During phases 1a and 1b, plasma insulin levels remain normal; the transition from phase 1b to phase 3, however, is accompanied by a significant increase in insulin, coinciding with hyperphagia, weight gain and obesity." (PMID 41198044, 2025). "Obesity induces numerous cellular stresses and inflammatory signaling pathways by ectopic accumulation of fat in various tissues, leading to insulin resistance." (PMID 40366502, 2025). "The shift from the M1 to the M2 phenotype decreases adipose tissue inflammation and increases insulin sensitivity, in addition to reducing the metabolic complications observed in obesity, a shift promoted by lifestyle changes, particularly exercise." (PMID 41373743, 2025). "Study results showed that replacing saturated fats with unsaturated fatty acids reduced hypothalamic inflammation, improved insulin sensitivity, and decreased adiposity in an animal model of obesity." (PMID 41301434, 2025). "Mouse studies have shown that miR-155 knockout affects insulin sensitivity, which supports the important role of this miRNA in metabolic disorders and provides a direct link between miR-155 levels and the obesity phenotype." (PMID 40943138, 2025). "Mounting evidence implicates that obesity represents a state of long-term, low-grade inflammation, and ATMs are a significant contributor to systematic inflammation and dysfunctional insulin action in obese individuals." (PMID 40368890, 2025). "For instance, fatty acid transport and insulin resistance support the metabolic adaptability of minipigs, making them suitable models for obesity research." (PMID 40121435, 2025). "The IRF4 gene, which is significantly downregulated in periodontitis, confers resistance to obesity and enhances insulin sensitivity following specific knockout in mice." (PMID 40606607, 2025). "Cardiometabolic phenotypes such as obesity and impaired insulin action are key determinants of type 2 diabetes (T2D)." (PMID 41373473, 2025). "Potassium imbalances in obesity arise due to a combination of renal dysregulation, insulin resistance, and RAAS overactivation." (PMID 40136609, 2025).